LEP (leptin)
Diseases named in the same sentence as LEP in open-access papers (continued):
Sharing a sentence is not in itself a finding about the gene and the disease.
autoimmune disease (continued). "Based on leptin’s role in autoimmune diseases and cancer, several leptin and leptin receptor (LR) antagonists have been developed, but these intrinsically lead to unwanted weight gain." (PMID 30659329, 2019). "There is now emerging evidence to suggest that leptin has proinflammatory effects in multiple autoimmune disease including SLE, RA, and multiple sclerosis (MS)." (PMID 30712132, 2019). "High levels of leptin correlate with a reduced number and with decreased functions of Treg cells in human autoimmune diseases." (PMID 31091785, 2019). "Altogether, leptin signaling appears to provide an important link between nutritional status and autoimmune disease through its effects on T cell metabolism and function." (PMID 29868016, 2018). "Leptin and LepR-deficient mouse models presented augmented number and activity of Treg cells together with a resistance to autoimmune diseases, and leptin replacement rescues Treg cell levels to wild-type mice values." (PMID 29910742, 2018). "Observed changes in Leptin favor pro-inflammatory cell responses and can directly influence development of autoimmune disease mediated by Th1 immunity." (PMID 29497108, 2018). "Accordingly genetic deletion of leptin in mice, and the neutralization of leptin are shown to benefit autoimmune disease by restoring immune cell functions." (PMID 30337927, 2018). "Given the role of leptin in regulating the balance between Teff and Treg cells, multiple studies have examined the effect of leptin on autoimmune diseases." (PMID 29868016, 2018). "Prolactin and Leptin influence the immune system and contribute to autoimmune diseases and inflammation." (PMID 30337927, 2018). "Recent studies have revealed that neutrophils play an important role in autoimmune diseases and that leptin also mediates their migration and metabolism as well as inhibiting their apoptosis, among other roles." (PMID 30169503, 2018). "Together, these results indicate that leptin plays a critical role in the development of autoimmune disorders and demonstrate that our transgenic leptin pigs can act as a valuable model of SLE." (PMID 30169503, 2018). "Recent evidence indicates that leptin promotes pro-inflammatory cytokine secretion, thus enhancing immune responses in autoimmune disorders." (PMID 24778633, 2014). "Leptin effect on autoimmune disease is mediated by a switch from a TH2 to TH1 pattern of cytokine release and consequent promotion of TH1 immune response and suppression of TH2 cell responses." (PMID 24900992, 2014). "Leptin has also been shown to play pro-inflammatory and immunomodulatory roles in various autoimmune diseases characterized by Th1 autoreactivity." (PMID 23840489, 2013). "Adipokines, especially leptin and adiponectin, have recently been reported to be involved in the development and regulation of some autoimmune diseases." (PMID 23144698, 2012). "Leptin and adiponectin have recently been found involved in the development and regulation of autoimmune diseases." (PMID 23144698, 2012). "Beside its key role in the regulation of food intake and energy expenditure, leptin is also involved in the pathogenesis of inflammatory and autoimmune disease." (PMID 17519037, 2007). "In addition, as a protein hormone, leptin also exerts potential functions in immune regulation and the pathogenesis of autoimmune diseases, such as the activation of monocytes, macrophages, neutrophils, and T lymphocytes." (PMID 36836789, 2023). "Accordingly, leptin mutants may be considered as antagonists and could be a hope for the control of leptin effects in the pathogenesis of autoimmune diseases." (PMID 35270000, 2022). "Conversely low leptin levels have been found to protect against autoimmune disease development." (PMID 36479348, 2022).
autoimmune disease (continued). "In a larger, systemic context, leptin is associated with numerous chronic, non-autoimmune, and autoimmune diseases, which is consistent with the picture of an increased inflammatory response following leptin treatment in the present study." (PMID 34202165, 2021). "This new insight into the immunomodulatory function of leptin could lead to future research and revolutionize drug discovery and development for patients with autoimmune diseases." (PMID 34299256, 2021). "Additional studies are warranted to further investigate the immunomodulatory function of leptin, which may be a target for the treatment of autoimmune diseases." (PMID 34299256, 2021). "In summary, regulation of leptinemia is complex and additional studies are necessary to clarify whether leptin is a real actor or a simple mediator in the inflammatory process of these autoimmune diseases." (PMID 32824322, 2020). "This increase of adipose tissue and of circulating leptin could contribute to the induction of autoimmune diseases by these drugs." (PMID 32781535, 2020). "Moreover, the function of the leptin gene in autoimmune diseases has received much attention in recent years." (PMID 33083462, 2020). "The role of leptin gene in autoimmune diseases has received much attention in recent years." (PMID 33083462, 2020). "It remains to be established if leptin could be a potential therapeutic target in treating human autoimmune diseases." (PMID 31091785, 2019). "Consequently, leptin can contribute to the onset and progression of several T cell-controlled autoimmune diseases, including Crohn’s disease, rheumatoid arthritis, multiple sclerosis and autoimmune hepatitis." (PMID 30659329, 2019). "Although not strictly an autoimmune disease, it is also notable that in an allogeneic skin-transplant model, leptin-deficient mice showed an increase in graft survival relative to wild-type mice." (PMID 29868016, 2018). "Leptin activity may be detrimental in some pathological conditions such as enhancement of undesired immune responses in chronic inflammatory diseases, autoimmune diseases, cancer, elevated blood pressure, and certain cardiovascular pathologies." (PMID 28490838, 2017). "Leptin production is elevated in experimental inflammation and in human autoimmune diseases." (PMID 27352030, 2016). "Reducing leptin levels could reduce adipose tissue inflammation and the ongoing inflammation that occurs in autoimmune diseases, but it also affects appetite and food intake." (PMID 25918733, 2015). "Further studies are needed in order to clarify whether leptin might represent a new disease activity biomarker and to explore its therapeutic potential in autoimmune diseases." (PMID 24799765, 2014). "Leptin has also been linked to spontaneous autoimmune disease such as Type 1 Diabetes (T1D) in the non-obese diabetic (NOD) mice." (PMID 24778633, 2014). "Although clinical significance of this elevation remains unknown leptin antagonists may represent new possibilities for the therapy of autoimmune disorders." (PMID 24900992, 2014). "The involvement of leptin in the pathogenesis of inflammatory and autoimmune diseases allows us to believe that prevention of leptin-induced inflammation may bring benefits to both RA and SLE subjects." (PMID 22584415, 2012). "Regarding the effects of leptin in the modulation of cytokine production, studies have shown that it can induce the expression of inflammatory cytokines that play a role in the development of autoimmune diseases." (PMID 19888448, 2009). "These discrepancies observed in the different studies may be related to different factors such as the confounding factors resulting from the co-existence of other autoimmune diseases in RA patients, methods of leptin measuring, small sample sizes, different treatments given, etc.." (PMID 35270000, 2022).
autoimmune disease (continued). "Leptin at the crossroad between inflammation, metabolism, and immunity in joint diseases, could provide new therapeutic approaches to improving outcomes for patients suffering from rheumatic diseases and autoimmune disorders." (PMID 35270000, 2022). "In human autoimmune patients, elevated serum leptin levels occur in certain diseases and may play a causal role in the disease progress although a direct link of leptin to human autoimmune disease pathogenesis has not been yet established." (PMID 22815836, 2012). "In this work, we investigated the role of leptin in childhood ITP, an autoimmune disease that has clear stages that can be followed closely by platelet counts, and no underlying pathology." (PMID 34299256, 2021). "Hence, leptin can be pointed as a link between immune tolerance, metabolic function, and autoimmunity, and leptin signaling-directed strategies could provide future innovative therapies for autoimmune disorders like RA." (PMID 29910742, 2018). "Thus, LEP and LEPR gene polymorphisms might influence the production and activity of inflammatory cytokines and thereby play a role in the development of various autoimmune diseases." (PMID 28244652, 2017). "LEP could enhance the function of CD8+ T cells by increasing the expression level of IFN-γ, implying a notable relationship with autoimmune diseases." (PMID 37207234, 2023). "CD4+ T cell-derived leptin, but not plasma leptin, were positively correlated with the percentage of Th17 cells or RORγt levels in chronic lymphocytic thyroiditis, an organ-specific autoimmune disease." (PMID 29910742, 2018). "Research has found that leptin is Th17 necessary for lymphocyte differentiation; in addition, leptin and thymocytes from double-positive cells (CD4+ CD8+) to CD4+ differentiation of single positive cells-related Treg are needed to suppress the abnormal immune response in autoimmune diseases." (PMID 35027962, 2021). "In addition, adipocytes secrete various cytokines, such as leptin, adiponectin, IL-6, resistin, visfatin and TNF-α, which regulate the proliferation and differentiation of T cells and are involved in many chronic inflammatory and autoimmune diseases." (PMID 33329579, 2020). "Leptin is one of the most thoroughly investigated cell-signaling molecules secreted by the fat tissues and is typically elevated in patients diagnosed with lupus (systemic lupus erythematosus [SLE]), an autoimmune disease in which the body’s immune system attacks healthy tissues in many organs." (PMID 30169503, 2018). "Thus, leptin may be one of the mediators of inflammation responsible not only in autoimmune diseases but also in other inflammatory disorders." (PMID 32824322, 2020). "Taken together, these results suggest that leptin might act as a negative signal for the expansion of Foxp3+CD25+CD4+ and might be a potential therapeutic approach for autoimmune disease." (PMID 35270000, 2022).
osteoarthritis (70 papers, 2005 to 2026). A noninflammatory degenerative joint disease occurring chiefly in older persons, characterized by degeneration of the articular cartilage, hypertrophy of bone at the margins and changes in the synovial membrane. "MR reveals a causal relationship between adipokines, such as adipose transport proteins, leptin, and resistin, and the risk of osteoarthritis; however, the underlying mechanisms are more complex." (PMID 39172202, 2024). "The parsimonious model (model C) included only P3NP, leptin, fat mass, osteoarthritis, age, and sex that were all associated with variation of muscle density in the study times." (PMID 37532926, 2024). "The main findings from the literature highlight the association between osteoarthritis (OA) and elevated serum and synovial levels of leptin, chemerin, visfatin, and high plasma levels of resistin." (PMID 39409194, 2024). "The results have also suggested that LOXL3 plays a significant role in the pathogenesis of leptin-associated osteoarthritis." (PMID 35035830, 2022). "BMI was significantly associated with higher LEP promoter methylation levels in individuals with osteoarthritis." (PMID 31878053, 2019). "Leptin, a pro-inflammatory adipokine predominately expressed by subcutaneous adipose tissue is associated with bodily pain in women and leptin levels in both serum and synovial fluid are associated with osteoarthritis, particularly in women." (PMID 30021590, 2018). "This theory is supported by an observational study investigating knee joint changes using magnetic resonance imaging, where reduced cartilage volume, a hallmark of osteoarthritis, is associated with increased leptin." (PMID 30021590, 2018). "Adipokines adiponectin, leptin, and resistin were analyzed in all groups; however, the only association was observed with adiponectin and those with osteoarthritis." (PMID 29225423, 2017). "This meta-analysis investigated the clinical significance of leptin levels in osteoarthritis (OA) patients, with the goal of building a leptin-based diagnostic criterion for OA." (PMID 25893833, 2015). "Extremely high amounts of leptin have been reported in obese individuals, which can be associated with osteoarthritis (OA) development." (PMID 26636769, 2015). "The aim of this study was to describe the associations between leptin, IL-6, and hip radiographic osteoarthritis (ROA) in older adults." (PMID 20482813, 2010). "Therefore, we conducted a prospective and cross-sectional study to examine the associations between preoperative leptin levels with VTE after TKA in osteoarthritis (OA) patients." (PMID 29794796, 2018). "Much of the previous research in osteoarthritis suggested higher circulating adipokine levels in osteoarthritis patients, and although we observed higher adiponectin and leptin levels in participants with osteoarthritis, only adiponectin resulted in a significant association with osteoarthritis." (PMID 29225423, 2017). "Leptin has also been increasingly recognized to play a role in inflammation, angiogenesis, as well as cartilage and bone metabolism, and thus has been implicated in the development of osteoarthritis." (PMID 22651805, 2012). "In particular, leptin has engendered intense interest because it upregulates both catabolic and anabolic activities of chondrocytes, consistent with cellular changes associated with osteoarthritis." (PMID 20604941, 2010). "High leptin levels are associated with obesity, which is a risk factor for osteoarthritis." (PMID 15899045, 2005). "Eight markers were found to be associated with an increased risk of osteoarthritis, including serum testosterone, serum dihydrotestosterone, sex hormone-binding globulin, glycosylated hemoglobin (HbA1c), insulin-like growth factor-binding protein 4, lipocalin, leptin, and resistin." (PMID 39172202, 2024). "The causal relationship of the LEP-LEPR-CD31 signaling pathway in aging and osteoarthritis models is revealed at the overall and molecular levels." (PMID 41907290, 2026).
osteoarthritis (continued). "This project will provide a new theoretical basis for the pathogenesis of early OA and new ideas and targets for the clinical treatment of OA by exploring the LEP-LEPR-CD31 signaling in osteoarthritis." (PMID 41907290, 2026). "The expression of both leptin and adiponectin receptors have been identified on chondrocytes and subchondral osteoblasts, and subchondral osteoblasts in osteoarthritis overproduce leptin compared to normal cells." (PMID 39152660, 2025). "A strong relation was found between the mRNA level of LOXL3 and leptin SF in cartilage in samples from the rat model of osteoarthritis." (PMID 35035830, 2022). "mRNA of LOXL3 was increased in osteoarthritis models which were directly related to leptin concentration in SF." (PMID 35035830, 2022). "Many studies have reported an overexpression in leptin in the pathogenetic studies in the osteoarthritis model." (PMID 35035830, 2022). "We conclude that an increase in leptin in rats who were suffering from osteoarthritis have increased the LOXL3 expressions." (PMID 35035830, 2022). "Seahorse hydrolysate decreased some proinflammatory factors related to osteoarthritis development, such as reduction of tumor necrosis factor-alpha and leptin as well as oxidative stress." (PMID 35509713, 2022). "Obese patients with osteoarthritis have more leptin in their synovial fluid compared with lean patients." (PMID 34912237, 2021). "In this review, we will focus on the role of leptin in the regulation of cartilage homeostasis and its implication in the development of degenerative joint diseases such as OA." (PMID 33673730, 2021). "Level of leptin in synovial fluid of osteoarthritis patients undergoing total knee replacement surgery positively correlated with the levels of MMP-1 and MMP-3." (PMID 33396484, 2020). "This study was conducted to investigate the interaction of BMI with osteoarthritis on LEP promoter methylation." (PMID 31878053, 2019). "The interaction between osteoarthritis and BMI on LEP promoter methylation was significant (p-value = 0.0180)." (PMID 31878053, 2019). "LEP enhances osteoarthritis development by exerting pro-inflammatory and pro-catabolic actions on the cartilage, leading to articular degeneration which is typical of osteoarthritis." (PMID 31878053, 2019). "One study which examined adiponectin, leptin, and resistin found that all 3 adipokines were elevated in those with osteoarthritis; however, these patients all had severe osteoarthritis and were significantly older than control participants." (PMID 29225423, 2017). "Osteoarthritis (OA) is a metabolic disorder that is partly attributed to adipokines such as leptin, and we previously observed that glucocorticoids induced leptin secretion in OA synovial fibroblasts." (PMID 27716396, 2016). "Further subgroup analysis based on the source of sample showed that there was a positive connection between enhanced expression of leptin and the osteoarthritis development in both blood and SF subgroups." (PMID 25893833, 2015). "Elevated levels of circulating leptin and synovial leptin were reported in rheumatoid arteritis patients compared to controls or osteoarthritis patients." (PMID 24900992, 2014). "Exercising and changing diet composition, such as replacing fat by non-saturated fatty acids, can revert the inflammatory process and resistance to leptin, attenuating the speed of progression or preventing the emergence of osteoarthritis." (PMID 25184806, 2014). "For example, the 7q22 region, that contains the genes reelin (RELN) and leptin (LEP), is linked to several conditions including: osteoarthritis, autism, body mass index, and dilated cardiomyopathy." (PMID 23936524, 2013). "Leptin concentrations in synovial fluid were also significantly correlated with BMI in people with severe osteoarthritis." (PMID 22046513, 2011). "For leptin, several previous studies provide support for an indirect role of leptin in osteoarthritis pathogenesis." (PMID 20604941, 2010).